SMARCE1 (SWI/SNF related BAF chromatin remodeling complex subunit E1)
Description:
Involved in transcriptional activation and repression of select genes by chromatin remodeling (alteration of DNA-nucleosome topology). Component of SWI/SNF chromatin remodeling complexes that carry out key enzymatic activities, changing chromatin structure by altering DNA-histone contacts within a nucleosome in an ATP-dependent manner. Belongs to the neural progenitors-specific chromatin remodeling complex (npBAF complex) and the neuron-specific chromatin remodeling complex (nBAF complex). During neural development a switch from a stem/progenitor to a postmitotic chromatin remodeling mechanism occurs as neurons exit the cell cycle and become committed to their adult state. The transition from proliferating neural stem/progenitor cells to postmitotic neurons requires a switch in subunit composition of the npBAF and nBAF complexes. As neural progenitors exit mitosis and differentiate into neurons, npBAF complexes which contain ACTL6A/BAF53A and PHF10/BAF45A, are exchanged for homologous alternative ACTL6B/BAF53B and DPF1/BAF45B or DPF3/BAF45C subunits in neuron-specific complexes (nBAF). The npBAF complex is essential for the self-renewal/proliferative capacity of the multipotent neural stem cells. The nBAF complex along with CREST plays a role regulating the activity of genes essential for dendrite growth (By similarity). Required for the coactivation of estrogen responsive promoters by SWI/SNF complexes and the SRC/p160 family of histone acetyltransferases (HATs). Also specifically interacts with the CoREST corepressor resulting in repression of neuronal specific gene promoters in non-neuronal cells.
Synonyms: BAF57; CSS5
Tractability: Small molecule: a structure with a bound ligand is known. PROTAC: UniProt records ubiquitination sites on it; ubiquitination databases record sites on it; its protein half-life has been measured.
Gene: Protein-coding gene on chromosome 17 (40,624,962 to 40,648,654, reverse strand). Ensembl gene ENSG00000073584.
Subcellular location: Nucleus
Subcellular location (Human Protein Atlas): Nucleoplasm
Pathways (Reactome):
Chromatin organization: Formation of neuronal progenitor and neuronal BAF (npBAF and nBAF); Formation of the canonical BAF (cBAF) complex; Formation of the embryonic stem cell BAF (esBAF) complex; Formation of the polybromo-BAF (pBAF) complex; RMTs methylate histone arginines
Gene expression (Transcription): RUNX1 interacts with co-factors whose precise effect on RUNX1 targets is not known; Regulation of endogenous retroelements by Piwi-interacting RNAs (piRNAs)
Developmental Biology: Regulation of MITF-M-dependent genes involved in pigmentation
Gene Ontology:
Molecular function: ATP-dependent chromatin remodeler activity; N-acetyltransferase activity; nuclear receptor binding; nucleosomal DNA binding; protein binding; chromatin binding; transcription coactivator activity; RNA binding
Biological process: chromatin remodeling; negative regulation of DNA-templated transcription; nucleosome disassembly; positive regulation of cell differentiation; positive regulation of double-strand break repair; positive regulation of myoblast differentiation; positive regulation of stem cell population maintenance; positive regulation of T cell differentiation; regulation of G0 to G1 transition; regulation of G1/S transition of mitotic cell cycle; regulation of mitotic metaphase/anaphase transition; regulation of nucleotide-excision repair; regulation of transcription by RNA polymerase II; positive regulation of DNA-templated transcription
Cellular component: chromatin; nucleoplasm; nucleus; protein-containing complex; SWI/SNF complex; bBAF complex; brahma complex; kinetochore; nBAF complex; npBAF complex; nuclear chromosome; nuclear matrix; RSC-type complex
Genetic constraint (gnomAD): Loss-of-function variants: 5 observed, 33.1 expected, observed/expected ratio (o/e) 0.15, 90% interval 0.078 to 0.32. The upper end of that interval is the gene's LOEUF score, 0.32, which puts it in group 1 of 6, group 1 being the genes least tolerant of losing a copy. Missense variants: 240 observed, 390.53 expected, observed/expected ratio (o/e) 0.61, 90% interval 0.55 to 0.68. Synonymous variants: 115 observed, 128.82 expected, observed/expected ratio (o/e) 0.89, 90% interval 0.77 to 1.04.
Gene-disease validity (ClinGen):
ClinGen rates the evidence that SMARCE1 causes each of these diseases.
Coffin-Siris syndrome (autosomal dominant): Definitive. Coffin-Siris syndrome (CSS) is a rare congenital multi-systemic genetic disorder characterized by aplasia or hypoplasia of the distal phalanx or nail of the fifth digit, developmental delay, intellectual disability, coarse facial features, and other variable clinical manifestations.
familial meningioma (autosomal dominant): Definitive.
Cancer hallmarks: escaping programmed cell death (suppresses); proliferative signalling (promotes); invasion and metastasis (promotes)
Homologues: Orthologues: chimpanzee SMARCE1 (100% identical), macaque SMARCE1 (100% identical), pig SMARCE1 (98% identical), rabbit SMARCE1 (98% identical), mouse Smarce1 (97% identical), rat Smarce1 (97% identical), guinea pig SMARCE1 (96% identical), dog SMARCE1 (90% identical), tropical clawed frog smarce1 (89% identical), zebrafish smarce1 (76% identical), Drosophila melanogaster Bap111 (48% identical), Caenorhabditis elegans hmg-4 (9% identical), and 1 more. Paralogues in human: TOX3 (20% identical), HMG20B (19% identical), TOX4 (18% identical), TOX2 (17% identical), TOX (17% identical), HMG20A (16% identical), UBTF (16% identical), SP100 (14% identical), HMGXB4 (12% identical), SP140 (12% identical), HMGB3 (11% identical), SP140L (10% identical), and 8 more.
Diseases named in the same sentence as SMARCE1 in open-access papers:
SMARCE1 is named in the same sentence as 78 diseases in open-access papers, as found by Europe PMC text mining. Sharing a sentence is not in itself a finding about the gene and the disease. The quoted sentences say what the papers report.
meningioma (34 papers, 2016 to 2025). A generally slow growing tumor attached to the dura mater. "We confirmed known associations, such as PTCH1 with MB, SMARCB1 with ATRT, and SMARCE1 with meningioma (MNG)." (PMID 39974082, 2025). "Clear cell meningioma is characterized by a SMARCE1 mutation and is different from other types of meningiomas." (PMID 38321548, 2024). "A recent study investigating the epigenomics of clear cell meningiomas found a unique SMARCE1 mutation signature, bridging mutations in SMARCE1 to the observed epigenomic changes." (PMID 34846640, 2022). "In summary, our data demonstrate a highly distinct epigenetic signature of clear cell meningiomas, that is associated with frequent mutations within the SMARCE1 gene and/or loss of SMARCE1 protein expression, presumably by other mechanisms." (PMID 33319313, 2021). "Genetically, an enrichment of loss-of-function mutations in the SMARCE1 gene encoding a subunit of the SWI/SNF chromatin remodeling complex has been reported for this meningioma subtype." (PMID 33319313, 2021). "As SMARCE1 mutations were detected in almost all tumors analyzed, it seems that clear cell meningiomas are primarily driven by these alterations." (PMID 33319313, 2021). "Another study demonstrated a highly distinct epigenetic signature of clear cell meningiomas, which was associated with frequent mutations within the SMARCE1 gene and/or loss of SMARCE1 protein expression." (PMID 35004283, 2021). "Our findings indicate the existence of a highly distinct epigenetic signature of clear cell meningiomas, separate from all other variants of meningiomas, with recurrent mutations in the SMARCE1 gene." (PMID 33319313, 2021). "SMARCE1 mutations are frequently seen in patients that present with spinal meningiomas with clear cell histology." (PMID 33801089, 2021). "Beyond the NF2, the SMARCE1 (SWI/SNF-related, matrix-associated, actin-dependent regulator of chromatin, subfamily E, member 1) gene mutation was found in young adults (16–24 years) with meningioma." (PMID 34574050, 2021). "Males with a symptomatic SMARCE1 mutation developed meningiomas in childhood (age range 2–10 years), while females developed tumors later in adolescence or early adulthood (age range 14–30 years)." (PMID 33801089, 2021). "All symptomatic males with a SMARCE1 mutation described so far developed meningiomas in childhood (age range 2–10 years), while the symptomatic carrier females developed tumors somewhat later in adolescence or early adulthood (age range 14–30s)." (PMID 26803492, 2016). "This case report shows further evidence for the role of SMARCE1 mutations in the etiology of clear cell meningiomas." (PMID 26803492, 2016). "Virtually, all clear cell meningiomas carry SMARCE1 mutations." (PMID 40356449, 2025). "Immunostaining revealed SMARCE1 mutations in both cases of clear cell meningiomas." (PMID 38819451, 2025). "However, additional studies are needed to clarify the mechanisms underlying SMARCE1-related clear cell meningioma development." (PMID 39868379, 2024). "Further work is required to elucidate the mechanism of SMARCE1-associated meningioma development." (PMID 38321548, 2024). "Whether germline mutations in the SMARCE1 gene are associated with an increased risk for developing multiple meningiomas, as initially suggested, has to be determined in subsequent studies." (PMID 33319313, 2021). "In addition, screening of 705 meningioma samples with available sequencing and DNA methylation data revealed that SMARCE1 mutations occurred exclusively within the specific epigenetic class of clear cell meningiomas." (PMID 33319313, 2021). "Besides confirming the known association of SMARCE1 mutations and clear cell meningioma, our findings indicate the existence of a highly distinct epigenetic signature of this meningioma subtype." (PMID 33319313, 2021).
meningioma (continued). "Because of the few reported cases so far, the lifetime risk of developing meningiomas for SMARCE1 mutation carriers is unclear and the complete tumor spectrum is unknown." (PMID 26803492, 2016). "However, patients with a history of a SMARCE1-related meningioma will probably remain at a higher risk for further CCMs, particularly if female." (PMID 26803492, 2016). "However, given that SMARCE1 is itself a broad epigenetic regulator, this could explain why the DNA methylation profile in SMARCE1 deficient meningiomas is so different from that of other meningiomas." (PMID 33319313, 2021). "In some cases, germline mutations in genes are thought to be related to meningioma initiation and progression, e.g., in the SMARCB1 and SMARCE1 mutations." (PMID 40283561, 2025). "Instead, Grade 2 meningiomas showed an allocation to the MCs ‘benign’ (approximately two‐thirds), ‘intermediate’ (just over one‐third), ‘malignant’ (3%) and SMARCE1‐altered (1.6%)." (PMID 40356449, 2025). "We first examined how meningiomas of Grades 1, 2 and 3 and ungraded meningiomas allocate to the predicted MCs meningioma benign, intermediate, malignant and the MC meningioma, SMARCE1‐altered, and how these meningiomas resolve into the model scores of 0–9." (PMID 40356449, 2025). "Approximately 90% of Grade 1 meningiomas were allocated to the MC ‘benign’ and the remaining 10% to the MC ‘intermediate’ or, in a single case, to the class of SMARCE1‐altered." (PMID 40356449, 2025). "Clear cell meningiomas are known to be most prevalent in pediatric and adolescent meningiomas, and their molecular basis is defined by alterations of the SMARCE1 tumor suppressor gene." (PMID 34495383, 2021). "An interesting finding was that the fastest growing cranial meningioma (P6_C1) carried one-copy loss of ARID1A and SMARCE1, the subunits of SWI/SNF, and one-copy gain of SUZ12 and EZH1, the components of PRC2." (PMID 32724039, 2020). "Histological subtype–specific mutations, such as KLF4/TRAF7 in secretory meningiomas and SMARCE1 in clear cell meningiomas, were also not supported by our assay." (PMID 40951339, 2025). "In CCM, mutations in the SMARCE1 gene occurred in 33 out of 34 cases, and unlike other meningiomas, CCM tumors are derived from progenitor cells." (PMID 38321548, 2024). "Otherwise, mutation of SMARCE1 or BAP1, can rarely be found in WHO grade 2 or 3 meningiomas." (PMID 35892898, 2022). "Mutations in SMARCE1, BAP1, KLF4/TRAF7, TERT promoter, and CDKN2A/B deletion, H3K27me3 loss and methylation profiling are now officially associated with the classification and grading of meningiomas." (PMID 34846640, 2022). "In addition, quantification of mRNA expression confirmed decreased SMARCE1 expression in tumors within the clear cell cohort as compared to NF2-altered meningiomas (adjusted p = 1.34e-11)." (PMID 33319313, 2021). "For example, secretory meningiomas show frequent co-mutations of the KLF4 and TRAF7 genes, while clear cell meningiomas show SWI/SNF-related, matrix-associated, actin-dependent regulators of chromatin, subfamily e, member 1 (SMARCE1) mutations." (PMID 33014773, 2020). "In addition, certain meningiomas harbor mutations in genes such as KDM5C, KDM6A, SMARCB1, and SMARCE1, which encode proteins involved in transcriptional chromatin remodeling (SMARCB1, SMARCE1) or histone demethylation (KDM5C, KDM6A)." (PMID 40787520, 2025). "For people with only meningiomas, germline testing may also include SMARCE1 and SUFU, which are rare causes of predisposition to non-NF2-related meningiomas." (PMID 41284083, 2025). "No NF2 alterations were found in our pediatric cases, and we could not assess SMARCE1 mutations in the clear-cell meningioma due to limited NGS panel coverage." (PMID 40951339, 2025).
meningioma (continued). "Conversely, there was no good scientific reason to exclude SMARCE1 loss-related familial meningioma or cohorts of patients with multiple meningioma as no confounding factors could be identified that would have hampered the COS development process." (PMID 38596715, 2024). "Recent studies have also illustrated the mutations in TERT promoter regions in grade III meningiomas, along with alterations in SMARCE1 and BAP1 that have been reported widely in clear cell and the rhabdoid subset of meningiomas." (PMID 37770851, 2023). "Meningiomas occur with greater frequency in patients with germline mutations of genes such as type-2 neurofibromatosis (NF2), type-1 neurofibromatosis (NF1, 19–24% of adolescent meningiomas), type-1 multiple endocrine neoplasia (MEN1), SMARCB1, LZTR1, or SMARCE1 genes." (PMID 37760490, 2023). "None of the ungraded meningiomas were classified as SMARCE1‐altered." (PMID 40356449, 2025). "Interestingly, SMARCE1 mutations seem to be restricted to this specific epigenetic class of clear cell meningiomas since no SMARCE1 alterations were found in 705 other meningioma samples with available DNA methylation and sequencing data." (PMID 33319313, 2021).
Coffin-Siris syndrome (13 papers, 2015 to 2024). "Missense variants in the SMARCE1 gene are known to cause Coffin–Siris syndrome (CSS), which is a rare congenital syndrome." (PMID 30548424, 2019). "Missense mutations in the SMARCE1 gene cause a clinically very different syndrome called Coffin-Siris syndrome (OMIM 135900) with congenital mental retardation and dysmorphisms as main features." (PMID 26803492, 2016). "It is currently unclear if missense mutations in the SMARCE1 gene causing Coffin-Siris syndrome predispose to CCMs later in life." (PMID 26803492, 2016). "Mutations in other genes involved with the SWI/SNF complex such as ARID1A, SMARCA2, SMARCA4, SMARCB1 and SMARCE1 are also responsible for Coffin-Siris syndrome." (PMID 26376624, 2015). "The so far known CCM patients with a loss-of-function SMARCE1 mutation have no clinical signs of Coffin-Siris syndrome, and screening for developmental delay or dysmorphisms is therefore not necessary." (PMID 26803492, 2016). "First described in 1970, Coffin–Siris syndrome is an intellectual disability disorder that is caused by mutations in genes encoding individual subunits of the BAF (BRG1/BRM-associated factor) complex, including ARID1A, ARID1B, SMARCA2, SMARCA4 (BRG1), SMARCB1 (INI1), and SMARCE1 (BAF57)." (PMID 26103525, 2015). "Sequence variants in other BAF complex genes are associated with other neurodevelopmental disorders including SMARCC1/2, PBRM1, ARID1A/B and SMARCA4 in ASD, PBRM1 and ARID1B in schizophrenia, SMARCB1 in Kleefstra syndrome, and ARID1A/B, SMARCA4, SMARCB1, and SMARCE1 Coffin-Siris syndrome (CSS)." (PMID 31288860, 2019).